EEF1A1P11 (eukaryotic translation elongation factor 1 alpha 1 pseudogene 11)
Synonyms: formerly EEF1AL9
Gene: Processed pseudogene on chromosome 1 (96,446,930 to 96,448,318, forward strand). Ensembl gene ENSG00000228502.
Diseases named in the same sentence as EEF1A1P11 in open-access papers:
EEF1A1P11 is named in the same sentence as 1 disease in open-access papers, as found by Europe PMC text mining. Sharing a sentence is not in itself a finding about the gene and the disease. The quoted sentences say what the papers report.
tumor (1 paper, 2022). "Compared to HPV negative, patients with HPV positive had significantly higher expressions of oncogene pseudogenes (SDHAP1, SDHAP3, DDX12P, CLUHP3, and RRN3P3), but there was no prominent difference in the expressions of tumor-suppressor pseudogenes (PDIA3P1, LDHAP4, LDHAP7, EEF1A1P6, and EEF1A1P11)." (PMID 36438489, 2022).